GPX4 (glutathione peroxidase 4)
Diseases named in the same sentence as GPX4 in open-access papers (continued):
Sharing a sentence is not in itself a finding about the gene and the disease.
liver cancer (42 papers, 2015 to 2026). An epithelial or non-epithelial malignant neoplasm that arises from the liver. "Ketamine therapy had a detrimental effect on lncPVT1 levels, which caused liver cancer cells to undergo ferroptosis and demonstrated the potential advantages of using the lncPVT1/miR-214-3p/GPX4 axis as a target for groundbreaking therapeutics." (PMID 38738178, 2024). "In terms of clinical application, the GPX4 agonist selenomethionine (Se-Met) upregulates GPX4 expression in a liver cancer model, and in combination with a PD-1 antibody, it significantly improves the complete response rate (CR)." (PMID 40535125, 2025). "Heteronemin, a marine terpenoid, triggers the apoptosis and ferroptosis of liver cancer cells by downregulating GPX4." (PMID 38892270, 2024). "Further experiments in liver cancer cells validated this, showing a significant decrease in GPX4 levels in MHCC97H/shPLAG1 cells when compared to the control group." (PMID 38745179, 2024). "Solasonine, a Solanum melongena-derived natural product, inhibits proliferation and promotes the ferroptosis of liver cancer cells by downregulating ferroptosis-inhibiting genes (GPX4 and GSS)." (PMID 38892270, 2024). "GPX4 uses glutathione to reduce LPOs into phospholipid molecules, making its role vital in boosting the cell's antioxidant capacity, which helps protect liver cancer cells from ferroptosis." (PMID 38745179, 2024). "It was shown to downregulate GPX4 expression and upregulate miR-214-3p levels through the lncPVT1/miR-214-3p/GPX4 regulatory axis, thus promoting ferroptosis in liver cancer cells." (PMID 37240889, 2023). "CircIL4R acts as a miR-541–3p sponge to regulate its target gene Gpx4; thus, circIL4R acts as a tumor promoter and ferroptosis inhibitor in liver cancer through the miR-541–3p/Gpx4 network." (PMID 35688814, 2022). "For another example, miR-214-3p can inhibit tumor by targeting GPX4 to induce ferroptosis in liver cancer cells, while in another study, miR-214-3p can aggravate ferroptosis in cisplatin induced acute kidney injury by targeting GPX4." (PMID 36408273, 2022). "Ferroptosis is mainly regulated by system Xc- and GPX4 and affecting the activity of system Xc- or GPX4 can induce ferroptosis of liver cancer cells." (PMID 35252001, 2022). "That is, ketamine regulates the ferroptosis process of liver cancer cells through the lncPVT1/miR-214-3p/GPX4 axis." (PMID 36408273, 2022). "Recently, we have identified the role of TRIB2 to relieve oxidative damage in liver cancer cells via declining the availability of Ub that for the ubiquitination of GPX4." (PMID 34315867, 2021). "In addition, relevant studies have shown that the expression level of GPX4 in B1/MZ B cells in tumor tissue from liver cancer patients is significantly lower than that in normal tissue, while the expression of 5-LOX is significantly higher." (PMID 40535125, 2025). "It has been shown that the overexpression of LncRNA plasmacytoma variant translocation 1 (PVT1), which is associated with multiple cancer types, can modulate the expression levels of GPX4 by suppressing miR-214-3p, hence promoting ferroptosis inhibition in liver cancer." (PMID 38738178, 2024). "Indeed, ketamine treatment negatively affected lncPVT1 levels, leading to ferroptosis onset in liver cancer cells and proving the potential benefits of targeting lncPVT1/miR-214-3p/GPX4 axis as novel therapeutic approach." (PMID 37132605, 2024). "Our GSEA enrichment analysis on the TCGA database indicates a strong connection between PLAG1 co-expression genes and redox reactions, suggesting GPX4 could be an influential mediator of PLAG1 in liver cancer." (PMID 38745179, 2024).
liver cancer (continued). "Furthermore, inhibiting miR-541-3p promotes the proliferation and inhibits the ferroptosis of liver cancer cells by upregulating GPX4, suggesting miR-541-3p is a ferroptosis-inducing miRNA." (PMID 38892270, 2024). "In short, the results of this study revealed LINC01134, a novel negative regulator of ferroptosis, up-regulates GPX4 expression by enhancing the recruitment of the transcription factor Nrf2 to the GPX4 promoter, thereby increasing liver cancer resistance to OXA." (PMID 35875091, 2022). "Furthermore, miR-214-3p has been proven to interact and bind to the 3ʹUTR of GPX4 in liver cancer cells, and GPX4 is also a direct target of miR-324-3p, which was downregulated in lung adenocarcinoma A549 cells." (PMID 35328568, 2022). "Currently, several conventional clinical drugs, such as the liver cancer‐targeting drug sorafenib and the anti‐inflammatory drug for inflammatory bowel disease, sulfasalazine, promote tumor cell ferroptosis by targeting key signaling pathways like Glutathione Peroxidase 4 (GPX4)." (PMID 41560416, 2026). "Thus, TRIB2 and PCBP2 maintain liver cancer cells viability via GPX4 to protect them against OS." (PMID 33414446, 2021). "GPX4 expression is regulated via microRNA (miRNA) binding to the 3′UTR in different cancer models, including lung, colorectal, prostate, and liver cancer (28, –, 31)." (PMID 39772623, 2025). "Tumor-specific GPX4 inhibition synergizes with anti-PD1 immunotherapy in murine models of pancreatic, colon and liver cancer." (PMID 40001204, 2025). "MiR-214-3p, in turn, competitively binds to GPX4, inducing iron-mediated apoptosis via PVT1/miR-214-3p/GPX4 axis in liver cancer (He GN." (PMID 40176927, 2024). "Dihydroartemisinin promotes the antiproliferation and ferroptosis of liver cancer cells by upregulating the ferroptosis-inducing ATF4 gene and downregulating ferroptosis-inhibiting genes (GPX4, SLC7A11, and SLC3A2)." (PMID 38892270, 2024). "Western blot results showed that the expression levels of GPX4 and SLC7A11 in the CK + AS1842856 group were increased compared with the CK group, indicating that CK induced ferroptosis in liver cancer cells through FOXO signaling pathway." (PMID 38664638, 2024). "A large number of studies have shown that ncRNAs can affect the progression of liver cancer by mediating various ferroptosis-related classical molecules or signals, such as SLC7A11, GPX4, and ACSL4." (PMID 37065473, 2023). "Mechanistically, glutathione peroxidase 4 functioned as one of the terminal effectors of TRIB2 and PCBP2 to protect liver cancer cells from oxidative damage." (PMID 33414446, 2021). "Several studies have shown that HSPA8 inhibits ferroptosis by promoting SLC7A11/GSH/GPX4 signalling and inhibiting NCOA4-mediated ferritinophagy, We verified the effects of HSPA8 in liver cancer and found that LACTB promotes ferroptosis by regulating HSPA8-mediated ferroptosis-related signalling." (PMID 39047638, 2024). "Reports have shown that GPX4 expression is obviously higher in the liver biopsy tissue among patients suffering liver cancer than in nontumor tissue." (PMID 35153782, 2022). "The regulation of GPX4 on liver cancer is mostly dependent on ferroptosis, and targeted suppression of GPX4 may be a novel path for non-surgical liver cancer treatment." (PMID 40969276, 2025).
myocardial infarction (42 papers, 2018 to 2026). Gross necrosis of the myocardium, as a result of interruption of the blood supply to the area, as in coronary thrombosis. "This is accompanied by downregulation of the antioxidant enzyme glutathione peroxidase 4 (GPx4), which is tightly associated with myocardial infarction." (PMID 40933952, 2025). "In the early and middle stages of myocardial infarction, GPX4 expression is markedly reduced, causing the accumulation of lipid peroxides and ultimately leading to ferroptosis." (PMID 39323645, 2024). "Deficiency or inhibition of Nrf2 exacerbated myocardial infarction–induced cardiomyocyte ferroptosis by reducing xCT and GPX4 expression, both in vivo and in vitro, suggesting that myocardial infarction is accompanied by cardiomyocyte ferroptosis." (PMID 40124544, 2025). "Conversely, miR-15a-5p, a direct target of GPX4, exacerbates ferroptosis and aggravates hypoxia-induced cardiomyocyte injury when overexpressed, modulating ferroptosis in acute myocardial infarction (AMI)." (PMID 40384965, 2025). "A proteomic study found that a decrease in GPx4 levels exacerbates ferroptosis during acute myocardial infarction (MI)." (PMID 39942544, 2025). "Proteomic analysis based on tandem mass tag showed that GSH metabolic pathway was downregulated during myocardial ischemia, especially GPX4 in the early and middle stages of myocardial infarction." (PMID 39396974, 2024). "A recent analysis showed that resveratrol can alleviate myocardial damage by inducing KAT5/GPX4 and inhibiting iron death in myocardial infarction." (PMID 38659000, 2024). "In another research study, EGR1 was regarded as a ferroptosis inducer in acute myocardial infarction because it inhibited GPX4 to promote ferroptosis via miR-15a-5p." (PMID 38397780, 2024). "By contrast, cardiac GPX4 was significantly reduced while Cx43 increased at DM 5 weeks (D5w) which was correspondent to significant increases in ferroptosis and myocardial infarction." (PMID 39310260, 2024). "Geniposide (GEN), a substance extracted from thetraditional Chinese medicine Gardenia, can reverse myocardial infarction-inducedoxidative stress and ferroptosis by targeting the Grsf1/GPX4 axis, and play acardioprotective role." (PMID 39076494, 2024). "ALDH2 deficiency enlarged myocardial infarct size, increased CK-MB, LDH and 4-HNE; iron accumulation; MDA production; glutathione depletion; GPX4 inactivation; increased ACSL4 and TfR1; downregulated FTH1and GPX4." (PMID 37942067, 2023). "It has been used to treat a variety of chronic inflammatory disorders, and by activating GPX4, it can reduce myocardial infarction by regulating the oxidative stress and ferroptosis driven on by iron overload." (PMID 37181809, 2023). "The Egr-1 regulates ferroptosis in acute myocardial infarction through miR-15a-5p/GPX4 axis, while GPX4 regulated mitochondria-mediated apoptosis through regulation of Egr1 in TNBC cells." (PMID 36238640, 2022). "In summary, we concluded that Res attenuated myocardial injury by inhibiting ferroptosis via inducing KAT5/GPX4 in myocardial infarction." (PMID 35685642, 2022). "A quantitative proteomic analysis showed that GPX4 expression was significantly downregulated in the prophase of myocardial infarction in mice." (PMID 36238649, 2022). "In a previous study, it has been reported that downregulation of GPX4 during the early and middle stages of myocardial infarction contributes to ferroptosis in cardiomyocytes upon metabolic stress such as cysteine deprivation." (PMID 35082973, 2022). "Furthermore, polyphenol drugs that inhibit ferroptosis were found to alleviate myocardial injury through the KAT5/GPX4 pathway in myocardial infarction." (PMID 40124544, 2025). "For instance, in a mouse model of myocardial infarction, the protein glutathione peroxidase 4 (GPX4), which plays a protective role against ferroptosis by targeting lipid peroxides, is found to be downregulated during the early and middle stages of the disease." (PMID 39341589, 2024).
myocardial infarction (continued). "Moreover, GPX4 was found to be downregulated in cardiomyocytes with myocardial infarction or diabetic myocardial ischemia/reperfusion injury." (PMID 38987672, 2024). "Additionally, Ferrostatin-1, an inhibitor of ferroptosis, can reduce myocardial infarction size by increasing glutathione peroxidase 4 (GPX4) expression and reducing the accumulation of iron and ROS via inhibition of endoplasmic reticulum stress." (PMID 39605920, 2024). "Therefore, by promoting the process oftranscription and translation of GPX4, ferroptosis in myocardial infarction canbe alleviated and exert a strong cardioprotective effect." (PMID 39076494, 2024). "GPX4 down-regulation during myocardial infarction results in ferroptosis in cardiomyocytes." (PMID 35805124, 2022). "Thus, we concluded that Res attenuated myocardial injury by inhibiting ferroptosis via inducing KAT5/GPX4 in myocardial infarction." (PMID 35685642, 2022). "The downregulation of GPX4 during myocardial infarction triggers ferroptosis in cardiomyocytes." (PMID 35805124, 2022). "The specific downregulation of GPX4 indicates that GPX4 may play a role in the occurrence and development of certain pathological processes during myocardial infarction." (PMID 36238649, 2022). "These interesting studies suggest that increasing GPX4 expression in the heart may help prevent ferroptosis, a contributor to myocardial infarction (MI)." (PMID 34639053, 2021). "In addition, resveratrol pretreatment can increase the expression of lysine acetyltransferase 5 and GPX4 in rat myocardial infarction model, suggesting that resveratrol can inhibit cardiomyocyte ferroptosis and alleviate cardiac dysfunction caused by myocardial infarction." (PMID 39744170, 2025). "DEX significantly alleviated myocardial infarction and decreased accumulation of Fe2+ and lipid peroxidation in cardiomyocytes.DEX significantly increased the expression levels of NRF2 and GPX4." (PMID 40949160, 2025). "Studies have shown that RES significantly inhibits the expression of ferroptosis‐related signals and mitigates mitochondrial damage by inducing SIRT1/GPX4 or KAT5/GPX4 pathways, ultimately improving outcomes in myocardial infarction." (PMID 40502812, 2025). "Our study also showed upregulated GPX4 and SLC7A11 improved cardiac function and reduced myocardial infarction size in the I/R-MMA + FER-1 group, as compared to the I/R-MMA group." (PMID 38238728, 2024). "In contrast, RSL3, an activator of ferroptosis, reduced GPX4 and SLC7A11 expression, suggestive of ferroptosis activation, which led to a decrease in cardiac function and an increase in the myocardial infarct size." (PMID 38238728, 2024). "Resveratrol has shown promising effects inalleviating myocardial injury induced by myocardial infarction, and recentresearch has shed light on its mechanism of action by targeting the Lysine(K)acetyltransferases 5 (KAT5)/GPX4 axis." (PMID 39076494, 2024). "Hetero deletion of Gpx4 aggravates myocardial infarct size of MIRI, and the overexpression of cytosolic Gpx4 suppressed cell death induced by OGD/R, which is in agreement with our data." (PMID 37623357, 2023). "Deferoxamine treatment decreased myocardial infarct size and serum CK activity; decreased ACSL4 and MDA levels; upregulation of GPX4." (PMID 37942067, 2023). "During the early and intermediate stages of myocardial infarction, inflammation and immune pathways are activated due to cysteine deprivation, and GSH and GPX4 levels are significantly decreased." (PMID 37181809, 2023). "Since many cellular pathways including inflammatory and metabolic pathways are altered during myocardial infarction in vivo, we could not exclude the possible contribution of the cardiac microenvironment to GPX4 protein levels and ferroptosis sensitivity." (PMID 31685805, 2019).
myocardial infarction (continued). "More recently, a proteomic study revealed that the downregulation of GPX4 exacerbates ferroptosis, a form of iron-dependent nonapoptotic cell death, during acute myocardial infarction (MI)." (PMID 34639053, 2021).
non-small cell lung carcinoma (42 papers, 2021 to 2026). A group of at least three distinct histological types of lung cancer, including non-small cell squamous cell carcinoma, adenocarcinoma, and large cell carcinoma. "BT’s ability to cause lipid peroxidation was significantly reduced in GPX4 deficiency, indicating that BT is dependent on GPX4 for inducing ferroptosis in non-small cell lung cancer." (PMID 40969276, 2025). "Bufotalin (BT), a novel GPX4 inhibitor, increases the degradation of GPX4 and intracellular Fe2+ level, causing ferroptosis in non-small cell lung cancer cells." (PMID 37458878, 2023). "Glutathione peroxidase 4 (GPX4) inhibition-driven ferroptosis has overcome drug resistance in non-small cell lung cancer (NSCLC)." (PMID 40257494, 2025). "In particular, in Kelch-like ECH-associated protein 1 (KEAP1) mutant non-small cell lung cancer (NSCLC), the overexpression of FSP1 induced cross-resistance to GPX4 inhibitors." (PMID 40559667, 2025). "Bufotalin (BT), a naturally occurring small molecule, has been shown in studies to induce ferroptosis in non-small cell lung cancer, with the mechanism relying on BT-induced GPX4 ubiquitination." (PMID 40969276, 2025). "For example, enhanced ferroptosis as a result of GPx4 inhibition increases the sensitivity of colorectal cancer to oxaliplatin, non-small-cell lung cancer to lapatinib, and Epstein–Barr-virus-infected nasopharyngeal carcinoma to platinum." (PMID 39125992, 2024). "For instance, it has been reported that BT-induced non-small cell lung cancer cell ferroptosis significantly inhibited its proliferation by promoting the degradation of GPX4." (PMID 39456433, 2024). "SAG hinders the development and spread of non-small cell lung cancer by controlling STUB1/GPX4-dependent ferroptosis." (PMID 38738178, 2024). "CircDTL inhibits ferroptosis and apoptosis of non-small cell lung cancer (NSCLC) cells through the circDTL/miR1287-5p/GPX4 axis." (PMID 37332354, 2023). "For example, GPX4 inhibitor-Bufotalin (BT), through facilitating the ubiquitination and degradation of GPX4, induces ferroptosis of non-small cell lung cancer (NSCLC) cells." (PMID 37840106, 2023). "Pyridinolone palladium complex (PdPT), a broad-spectrum deubiquitinase inhibitor, can promote the death of non-small cell lung cancer cells by inducing the degradation of GPX4 protein." (PMID 37005430, 2023). "Meanwhile, targeting GPX4 can also promote lapatinib (Lap) -induced ferroptosis in drug-resistant non-small cell lung cancer cells." (PMID 37005430, 2023). "This study aimed to evaluate the protein expression of glutathione peroxidase 4 (GPX4) in resected non-small cell lung cancer (NSCLC)." (PMID 36443446, 2022). "Furthermore, propofol mitigates cisplatin resistance in non-small cell lung cancer by downregulating GPX4 and inducing ferroptosis via the miR-744-5p/miR-615-3p pathway." (PMID 39935430, 2025). "Liang and his colleagues showed that an analog of erastin augmented cisplatin effects against non-small cell lung cancer cells by inducing ferroptosis detected by upregulation of ROS, and lipid peroxidation in addition to downregulated GPX4, the key regulator of ferroptosis inhibition." (PMID 39915547, 2025). "Furthermore, focusing on GPX4 has been shown to enhance lapatinib-induced ferroptosis in drug-resistant non-small cell lung cancer cells." (PMID 39944353, 2024). "In addition, it has been reported that NRF2 can upregulate GPX4 in non-small-cell lung cancer cells." (PMID 35983979, 2022). "Bufotalin (BT), a natural small molecule, was a novel glutathione peroxidase 4 (GPX4) inhibitor, which could trigger ferroptosis in non-small-cell lung cancer cells." (PMID 36613888, 2022).